MIR431 (microRNA 431)
Synonyms: hsa-mir-431; MIRN431; miRNA431; mir-431
Gene: MicroRNA gene on chromosome 14 (100,881,007 to 100,881,120, forward strand). Ensembl gene ENSG00000208001.
Homologues: Orthologues: chimpanzee ptr-mir-431 (100% identical), macaque mml-mir-431 (100% identical), rat Mir431 (96% identical), guinea pig MIR431 (79% identical), mouse Mir431 (79% identical), pig MIR431 (79% identical).